LINC00400 (long independently transcribed non-coding RNA 400)
Gene: Long non-coding RNA gene on chromosome 13 (43,158,631 to 43,159,466, forward strand). Ensembl gene ENSG00000229928.
Diseases named in the same sentence as LINC00400 in open-access papers:
LINC00400 is named in the same sentence as 1 disease in open-access papers, as found by Europe PMC text mining. Sharing a sentence is not in itself a finding about the gene and the disease. The quoted sentences say what the papers report.
colon cancer (1 paper, 2018). "We noted that 11 lncRNAs, SCARNA10, RPPH1, LINC01419, ERVH48-1, RMRP,CH507-513H4.3, MIR205HG, CH507-513H4.6, LINC00400, RP11-774D14.1 and AC006050.2, were also differentially expressed in colon cancer samples compared with the normal samples." (PMID 29420609, 2018).